GIPC1 (GIPC PDZ domain containing family member 1)
Diseases named in the same sentence as GIPC1 in open-access papers (continued):
Sharing a sentence is not in itself a finding about the gene and the disease.
tumor (23 papers, 2008 to 2026). "GIPC2 encodes a 315-amino acid protein that is 62% identical to GIPC1 and is considered a paralog of GIPC1 that promotes proliferation and invasion in tumor metastasis." (PMID 35347223, 2022). "GIPC2 is a GIPC1 paralog involved in WNT signaling pathways associated with tumor progression, but its role in PCa metastasis remains unclear." (PMID 35347223, 2022). "Similarly, NRP1 can associate with GIPC1 and promote tumor progression through the KRAS/ERK signaling pathway." (PMID 29018205, 2017). "While LNPs modified with targeting peptides effectively deliver GIPC1 mRNA to tumor cells in CRC CDX models, its distribution in healthy tissues remains unavoidable." (PMID 41522336, 2026). "In conclusion, this study reveals the GIPC1/TRIM21/TTC7B/mTOR/NF-κB tumor-suppressive axis in CRC and highlights the potential of GIPC1 for early diagnosis and overcoming chemoresistance in CRC patients." (PMID 41522336, 2026). "Tumor size was significantly reduced in the group treated with GIPC1-LNPs compared to the control group treated with carrier LNPs." (PMID 41522336, 2026). "To explore this potential, we employed targeting peptide-modified lipid nanoparticles (LNPs) to specifically deliver GIPC1 mRNA to tumor cells." (PMID 41522336, 2026). "Our initial findings confirm that GIPC1 suppresses tumor growth and decreases chemoresistance in CRC." (PMID 41522336, 2026). "Histological evaluation of H&E- and Ki67-stained tumor sections revealed that GIPC1-depleted tumors displayed pronounced morphological alterations accompanied by a marked downregulation of proliferative markers." (PMID 41155969, 2025). "Delivering GIPC1 siRNA via tumor-targeted liposomes provides a feasible approach for clinical application." (PMID 41155969, 2025). "Similar trends were observed in the 4636 tumors, where the combination treatment induced substantial inhibition of tumor growth, confirming that dual targeting of GIPC-1 and chemotherapy enhances therapeutic outcomes." (PMID 41155969, 2025). "In the single-mouse orthotopic pancreatic xenograft experiments using 6741, 4636, 4535, and 4911 tumor models, combination treatment with GIPC-1 siRNA and GEM consistently demonstrated superior antitumor efficacy compared to individual treatments or controls." (PMID 41155969, 2025). "Intravenous administration of the liposomal formulation complexed with GIPC1 siRNA inhibited tumor growth and significantly increased the GEM sensitivity in orthotopic pancreatic xenografts compared to that for the untreated control group." (PMID 41155969, 2025). "Using this lipopeptide, we engineered a novel tumor-targeted liposomal formulation encapsulating GIPC1-specific siRNA (LGIPCsi)." (PMID 41155969, 2025). "Stable knockdown or pharmacologic interference with the GIPC1 PDZ domain has previously been shown to inhibit tumor growth, highlighting its importance in PDAC progression." (PMID 41155969, 2025). "In line with this, our results demonstrate that siRNA-mediated knockdown of GIPC1 not only impairs tumor cell proliferation in vitro but also enhances the sensitivity of PDAC cells and xenografts to GEM." (PMID 41155969, 2025). "Combination therapy with GEM and GIPC1 siRNA produced a significant reduction in both tumor volume and tumor weight compared with monotherapies or control groups." (PMID 41155969, 2025). "We did not perform in vitro or in vivo manipulations (overexpression, knockdown, or knockout) of LRP2, CUBN, CAV1, GIPC1, or DAB2IP to establish causality between expression changes and tumor phenotypes." (PMID 41374987, 2025). "The purpose of this study was to develop and evaluate a novel tumor-targeted liposomal delivery system for RNAi against GIPC1 in PDAC." (PMID 41155969, 2025). "GIPC1 suppression reduced tumor growth and metastasis in mice intrasplenically transplanted with MACC1-overexpressing CRC cells." (PMID 38144523, 2023).
tumor (continued). "GIPC1 is a key protein involved in protein trafficking, endocytosis, receptor aggregation, and tumor occurrence and development." (PMID 38186571, 2023). "In conclusion, NRP and GIPC1 inhibition emerges as a promising avenue in PDAC treatment due to pleiotropic tumor-inhibitory effects." (PMID 31664117, 2019). "Taken together, this indicates that inhibitory effects on tumor cells upon GIPC1 or neuropilin knockdown are dependent on the assay rather than the cell line and the endogenous expression levels of the target genes." (PMID 31664117, 2019). "To test tumor-inhibitory effects of siRNA-mediated knockdown of GIPC1, NRP1 and NRP2 more rigorously in an in vivo model, we subcutaneously transplanted Colo357 cells into the both flanks of immunocompromised mice." (PMID 31664117, 2019). "By binding VEGF-A to NRP1, GIPC1 mediates the interaction between NRP1 and ABL1, which activates tyrosine kinase activity and associates with integrins, leading to induce tumor growth." (PMID 26209534, 2015). "Additionally, a subcutaneous tumor model in nude mice showed accelerated tumor growth upon GIPC1 knockdown." (PMID 41522336, 2026). "To determine whether GIPC1 mRNA inhibits tumor formation in vivo, we constructed a preclinical CDX-chemoresistance model." (PMID 41522336, 2026). "Building on our previous work demonstrating that GIPC1 is overexpressed in PDAC and associated with poor prognosis, the present study was designed to develop and evaluate a novel tumor-targeted liposomal delivery system (LGIPCsi) for RNA interference against GIPC1." (PMID 41155969, 2025). "By optimizing an LGIPCsi for stability, siRNA encapsulation, and selective tumor uptake, the research sought to overcome delivery challenges and assess the therapeutic efficacy of GIPC1 silencing alone or in combination with GEM in orthotopic and patient-derived xenograft models." (PMID 41155969, 2025). "By optimizing the LGIPCsi formulation for stability, siRNA encapsulation, and selective tumor uptake, we aimed to overcome delivery challenges and assess the therapeutic efficacy of GIPC1 silencing alone or in combination with GEM in orthotopic and patient-derived xenograft models." (PMID 41155969, 2025). "Additionally, four genes (i.e., COL6A1, SYDE1, ESCO2, and GIPC1) were differentially expressed between tumor and normal tissues." (PMID 34149809, 2021). "GIPC1 inhibition also significantly affected tumor growth in vivo." (PMID 31664117, 2019). "Little is known about the role of GIPC1 in tumor growth and progression." (PMID 21209904, 2010). "Moreover, the combination of GIPC1-LNPs with 5-FU resulted in further tumor shrinkage." (PMID 41522336, 2026). "The data demonstrated that liposomes loaded with GIPC1 mRNA effectively targeted CRC tumors and inhibited tumor progression in the cell-derived xenograft (CDX) model." (PMID 41522336, 2026). "To explore the potential mechanism by which GIPC1 influences CRC, we divided tumor patients in the GSE32323 dataset into high-expression and low-expression groups based on GIPC1 expression." (PMID 41522336, 2026). "In MACC1-driven CRC, GIPC1 acts as protein interaction partner and as transcription factor of MACC1, playing a dual role in tumor progression and metastasis." (PMID 41522336, 2026). "Specifically, LRP2 was significantly downregulated in RB compared to controls, whereas CUBN, DAB2IP, GIPC1, and CAV1 were significantly upregulated in tumor tissue." (PMID 41374987, 2025). "GAIP-interacting protein C-terminus 1 (GIPC1), a PDZ-domain-containing adaptor protein, is highly overexpressed in PDAC and plays a critical role in tumor progression and chemoresistance." (PMID 41155969, 2025). "In the 6741 tumors, both tumor volume and tumor weight were markedly reduced in the combination group relative to the control, empty liposome, GEM alone, or GIPC-1 siRNA alone." (PMID 41155969, 2025).
tumor (continued). "H&E staining revealed reduced tumor cellularity in the combination group, while Ki67 immunostaining demonstrated a marked decrease in proliferative index compared with GEM alone, GIPC1 siRNA alone, or controls." (PMID 41155969, 2025). "GIPC1 and DAB2IP, which regulate PI3K–AKT, ERK, and RhoA pathways, are predominantly reduced in dedifferentiated tumor subtypes, consistent with the release of growth-promoting signaling." (PMID 41374987, 2025). "The relevance of GIPC1 for tumor growth and metastasis was shown in mice intrasplenically transplanted with MACC1-overexpressing CRC cells, since GIPC1 knockdown reduced these MACC1-induced features." (PMID 38144523, 2023). "In this study, we directly compare the various tumor-inhibitory effects of transient RNAi-mediated depletion of NRP1, NRP2 and GIPC1, alone or in combination, in a set of cell lines with different expression levels." (PMID 31664117, 2019). "In this study, we have compared the various tumor-inhibitory effects following transient RNAi-mediated depletion of NRP1, NRP2 or GIPC1 either alone or in combination, in PDAC cell lines with different expression levels." (PMID 31664117, 2019). "These diverse oncogenic roles highlight the broad relevance of GIPC1 as a therapeutic target and suggest that strategies developed for PDAC may have applicability across multiple tumor types." (PMID 41155969, 2025). "However, notable protein-mRNA discordances emerged for CUBN, CAV1, DAB2IP, and GIPC1, which showed transcriptional upregulation in GSE208143 despite protein-level downregulation in most tumor subtypes." (PMID 41374987, 2025). "For the following in vivo experiments, we used the SW620 cells with high endogenous MACC1 expression treated with and without shGIPC1 RNA in order to prove for the effects of GIPC1 silencing on tumor growth and metastasis formation in xenografted mice." (PMID 38144523, 2023). "However, when diminishing GIPC1 expression in endogenously MACC1 high expressing cells, spleen tumor development and liver metastasis formation are reduced." (PMID 38144523, 2023). "Moreover, GIPC1 silencing decreased tumor growth and migration in BALB/c nude mice, while GIPC1 overexpression had contrasting effects." (PMID 38186571, 2023). "Another group reported that NRP1 augments the FN fibril assembly activity of integrin α5β1 by interacting with GIPC1 and c-Abl using its SEA motif and activates tumor microenvironment.These results provided evidence that NRP1 regulates cell adhesion dependent on integrin α5β1 function." (PMID 27863391, 2016). "Histological analysis revealed increased protein levels of GIPC1 and TTC7B in tumors treated with GIPC1-LNPs, while the Ki67 proliferation index was significantly elevated in the control group, especially the combination therapy of GIPC1-LNPs and 5-FU notably inhibited tumor proliferation." (PMID 41522336, 2026). "Importantly, no significant systemic toxicity was observed in treated animals; Conclusions: This study identifies GIPC1 as a promising therapeutic target in PDAC and demonstrates that tumor-targeted siRNA nanomedicine can effectively overcome chemoresistance when combined with standard chemotherapy." (PMID 41155969, 2025). "Indeed, in PCa, GIPC1 as a paralogous gene of GIPC2—which is involved in endosomal signaling and tumor cell proliferation, invasion, and metastasis —the PDZ domain of DVL binds the C-terminal region of Fzd receptors and is essential for WNT-signal transduction in PCa tumorigenesis." (PMID 35347223, 2022).
tumor (continued). "Of note, among the 6 proteins downregulated by NR-S:M in HepG2 cells, 5 of them (MRLP17, MDIG, GIPC1, NAGPA, FAM127A) were statistically and oppositely upregulated in LIHC vs. non-tumoral adjacent tumor (NTAT)." (PMID 38990489, 2025). "In conclusion, NRPs and GIPC1 emerge as promising targets in PDAC treatment due to pleiotropic, non-redundant tumor-promoting effects." (PMID 31664117, 2019).
benign tumors (2 papers, 2008 to 2010). "Our study, however, forms the basis for further broad-based research of the differential interaction of the fully human 27.B1 and 27.F7 autoantibodies with GIPC1 antigen in different malignant and benign tumors, which will likely be useful for research and diagnostics." (PMID 18721484, 2008).
infection (2 papers, 2021 to 2025). The state of being infected such as from the introduction of a foreign agent such as serum, vaccine, antigenic substance or organism. "Thus, the holdup assay enabled us to identify new host proteins potentially targeted by HBc during infection in addition to PTPN3 and GIPC1." (PMID 33441627, 2021).
movement disorder (2 papers, 2023 to 2025). Neurological conditions resulting in abnormal voluntary or involuntary movement, which may impact the speed, fluency, quality and ease of movement. "GGC repeat expansions in OPDM2 causative gene GIPC1 have been found to be associated with movement disorders." (PMID 40084170, 2025). "The GIPC1 gene is suspected to affect muscle motor function, which has an association with movement disorders in humans when CGG repeats are expanded." (PMID 37510415, 2023).
neurological diseases (1 paper, 2024). "Recent studies have implicated GLS, RAI1, GIPC1, MED15, EP400, MEF2A, and CNKSR2 in neurological diseases, with GLS, GIPC1, MED15, RAI1, and MEF2A sharing the same repeat loci reported in this study." (PMID 38871700, 2024).
GIPC1 also shares sentences with these, for which no sentence is quoted: breast tumors (3 papers); colon cancer (2); gastric cancer (2); ovarian serous carcinoma (2); pancreatic ductal adenocarcinoma (2); Adult onset (1); Ataxia (1); autism spectrum disorder (1); breast ductal carcinomas (1); breast ductal carcinomas in situ (1); breast fibroadenomas (1); breast hyperplasia (1); breast lobular carcinoma (1); breast lobular carcinomas in situ (1); co-infection (1); colorectal tumors (1); dentatorubral-pallidoluysian atrophy (1); fragile X syndrome (1); glioblastoma (1); hearing loss (1); HIV-1 infection (1); in situ carcinoma (1); Obesity (1); oculopharyngodistal myopathy 1 (1); ovarian borderline serous tumors (1); ovarian serous tumor (1); pancreas (1); parasitic infection (1); Parkinson’s (1); rectal adenocarcinoma (1).
A further 7 diseases each share a sentence with GIPC1 in 1 paper.